SCAMP5 (secretory carrier membrane protein 5)
Description:
Required for the calcium-dependent exocytosis of signal sequence-containing cytokines such as CCL5. Probably acts in cooperation with the SNARE machinery. May play a role in accumulation of expanded polyglutamine (polyQ) protein huntingtin (HTT) in case of endoplasmic reticulum stress by inhibiting the endocytosis pathway.
Synonyms: MGC24969
Tractability: Antibody: its Gene Ontology location is reachable by antibodies, with high confidence; UniProt places it where antibodies can reach, with medium confidence; UniProt predicts a signal peptide or a membrane-spanning region. PROTAC: its protein half-life has been measured.
Gene: Protein-coding gene on chromosome 15 (74,957,219 to 75,021,497, forward strand). Ensembl gene ENSG00000198794.
Subcellular location: Cell membrane; Golgi apparatus membrane; Golgi apparatus, trans-Golgi network membrane; Recycling endosome membrane; Cytoplasmic vesicle, secretory vesicle, synaptic vesicle membrane
Gene Ontology:
Molecular function: protein binding; protein-containing complex binding
Biological process: negative regulation of endocytosis; positive regulation of calcium ion-dependent exocytosis; positive regulation of cytokine production; response to endoplasmic reticulum stress; exocytosis; protein transport
Cellular component: Golgi membrane; membrane; plasma membrane; recycling endosome membrane; trans-Golgi network membrane; Golgi apparatus; synaptic vesicle membrane
Genetic constraint (gnomAD): Loss-of-function variants: 6 observed, 25.16 expected, observed/expected ratio (o/e) 0.24, 90% interval 0.13 to 0.47. The upper end of that interval is the gene's LOEUF score, 0.47, which puts it in group 2 of 6, group 1 being the genes least tolerant of losing a copy. Missense variants: 187 observed, 314.79 expected, observed/expected ratio (o/e) 0.59, 90% interval 0.53 to 0.67. Synonymous variants: 116 observed, 118.81 expected, observed/expected ratio (o/e) 0.98, 90% interval 0.84 to 1.14.
Homologues: Orthologues: chimpanzee SCAMP5 (99% identical), mouse Scamp5 (99% identical), dog SCAMP5 (98% identical), pig SCAMP5 (97% identical), rabbit SCAMP5 (97% identical), guinea pig SCAMP5 (94% identical), tropical clawed frog scamp5.2 (84% identical), rat Scamp5 (82% identical), zebrafish scamp5a (80% identical), macaque SCAMP5 (78% identical), zebrafish scamp5b (71% identical), Drosophila melanogaster Scamp (42% identical), and 1 more. Paralogues in human: SCAMP4 (57% identical), SCAMP2 (46% identical), SCAMP1 (45% identical), SCAMP3 (43% identical).
Diseases named in the same sentence as SCAMP5 in open-access papers:
SCAMP5 is named in the same sentence as 38 diseases in open-access papers, as found by Europe PMC text mining. Sharing a sentence is not in itself a finding about the gene and the disease. The quoted sentences say what the papers report.
autism (5 papers, 2021 to 2025). Persistent deficits in social interaction and communication and interaction as well as a markedly restricted repertoire of activity and interest as well as repetitive patterns of behavior. "By other hand, miR396 can affect the expression of the CMKLR1 gene, involved in cardiovascular diseases, and the SYVN1 and SCAMP5 genes, changes in the expression of which are associated with colon cancer and autism, respectively." (PMID 40001983, 2025). "Recent studies show that SCAMP5 is a candidate biomarker gene for autism and its downregulation is related to the synaptic dysfunction in autistic patients." (PMID 36203606, 2022).
Parkinson disease (5 papers, 2017 to 2025). A progressive degenerative disorder of the central nervous system characterized by loss of dopamine producing neurons in the substantia nigra and the presence of Lewy bodies in the substantia nigra and locus coeruleus. "Missense mutations in the human secretary carrier-associated membrane protein 5 (SCAMP5) cause a variety of neurological disorders including neurodevelopmental delay, epilepsy, and Parkinson’s disease." (PMID 37389974, 2023). "Moreover, disease-causing SCAMP5 mutations were reported in patients with intellectual disability, seizure, and Parkinson’s disease, a clinical spectrum that overlaps with T-type calcium channelopathies." (PMID 37389974, 2023). "Moreover, the two patients carrying SCAMP5 homozygous variants also suffered from Parkinson’s disease at the age of 18 and 16, respectively." (PMID 33390987, 2020). "As SCAMP5 suppresses autophagy and is a protein expressed at the synapse, we tested whether SCAMP5 may lead to the accumulation of α-synuclein, another synaptic protein whose accumulation causes Parkinson's disease." (PMID 28700687, 2017).
epilepsy (4 papers, 2020 to 2025). A brain disorder characterized by episodes of abnormally increased neuronal discharge resulting in transient episodes of sensory or motor neurological dysfunction, or psychic dysfunction. "We identified the same de novo heterozygous SCAMP5 variant in four unrelated patients with a consistent phenotype, including epilepsy, severe developmental delay, abnormal neurological exam findings, with or without ASD or dysmorphic features." (PMID 33390987, 2020). "Using WES, we identified the identical de novo heterozygous SCAMP5 variant (G180W) in four unrelated patients with a consistent phenotype, including epilepsy, severe developmental delay, abnormal neurological exams, and with or without ASD or variably dysmorphic features." (PMID 33390987, 2020). "SCAMP5 variant knock-in mice showed typical early-onset epilepsy similar to that of humans." (PMID 33390987, 2020). "Given that SCAMP5 and Cav3.2 channels are both candidate genes for epilepsy, and SCAMP5 R91W knock-in mice showed increased neuronal excitability, we also assessed the regulation of Cav3.2 in the presence of disease-causing SCAMP5 mutations." (PMID 37389974, 2023).
Huntington disease (4 papers, 2017 to 2025). Huntington disease (HD) is a rare neurodegenerative disorder of the central nervous system characterized by unwanted choreatic movements, behavioral and psychiatric disturbances and dementia. "Secretory carrier membrane protein 5 (SCAMP5) is a membrane protein induced in the brains of Huntington’s disease patients and its expression is regulated by transcription factor EB (TFEB), a transcriptional regulator of autophagy." (PMID 38525704, 2024). "On the other hand, SCAMP5 accumulates in the striatum of Huntington's disease patients and could aggravate mutant HTT aggregation, although the underlying mechanism was not clear." (PMID 28700687, 2017). "Here we show that SCAMP5, a secretory carrier membrane protein significantly induced in the brains of Huntington's disease patients, is quickly and transiently induced by protein stress and autophagic stimulation, and is regulated by the master autophagy transcriptional regulator TFEB." (PMID 28700687, 2017).
Sepsis (2 papers, 2022 to 2023). Sepsis is defined as life-threatening organ dysfunction caused by a dysregulated host response to infection. "SCAMP5 was preliminarily identified as a diagnostic marker of sepsis that may affect its progression by regulating ER stress." (PMID 36203606, 2022). "The diagnostic and therapeutic potential of SCAMP5 in sepsis warrants further investigation." (PMID 36203606, 2022). "Taken together, these findings suggest that SCAMP5 is a potential diagnostic marker for sepsis, and may play a vital role in its development." (PMID 36203606, 2022). "We confirmed the high expression levels of SCAMP5 mRNA and protein in PBMCs isolated from sepsis patients." (PMID 36203606, 2022). "SCAMP5 was significantly up-regulated in the sepsis samples compared to the control samples in both datasets (P < 0.05)." (PMID 36203606, 2022). "We then tested the expression levels of SCAMP5 in the PBMCs from sepsis patients (n = 5) and healthy donors (n = 5), and found that SCAMP5 protein and mRNA were both up-regulated in the PBMCs from sepsis patients compared to healthy controls." (PMID 36203606, 2022). "In addition, higher expression levels of SCAMP5 mRNA and protein were observed in PBMCs isolated from sepsis patients than healthy donors (n = 5)." (PMID 36203606, 2022). "ROC analysis further demonstrated that SCAMP5 could accurately predict sepsis, with AUC of 0.757 in GSE26378 and 0.637 in GSE54514." (PMID 36203606, 2022). "Moreover, SCAMP5 was preliminarily identified as a key driver of sepsis that may affect its progression by regulating ER stress." (PMID 36203606, 2022). "In sepsis, SCAMP5 shows promise for diagnosis biomarker, and the PI3K/Akt-HIF-1α pathway modulates immunological glycolysis, thereby controlling neutrophil function in sepsis patients." (PMID 38332910, 2023).
asthma (1 paper, 2020). "The hypermethylated genes have roles in asthma (VGLL4, AGR2), neurologic development (AGAP1, OTX2), and immune regulation (SCAMP5, SLC11A1)." (PMID 32850550, 2020).
bladder cancer (1 paper, 2025). "SCAMP5 is highly expressed in bladder cancer, breast cancer, esophageal cancer, lung cancer, melanoma, and leukemia." (PMID 40761243, 2025).
diabetes (1 paper, 2025). "This study demonstrates that hyperglycemia in diabetes activates ChREBP, which epigenetically represses SCAMP5 expression in pancreatic β‐cells." (PMID 40953307, 2025). "The reduction in SCAMP5 expression may be a result of hyperglycemia‐induced ChREBP overactivation in diabetes." (PMID 40953307, 2025).
glioma (1 paper, 2025). A benign or malignant brain and spinal cord tumor that arises from glial cells (astrocytes, oligodendrocytes, ependymal cells). "Following confirmation of the strong association between SCAMP5 gene expression and patient survival prognosis, our objective was to gain insight into the role of the SCAMP5 gene and its expression products in glioma tumor development." (PMID 40184123, 2025). "In order to ascertain the function of the SCAMP5 gene in glioma patients, the top 500 associated genes were selected from the Pearson correlation analysis (R > 0.5, descending order P < .05) and subjected to DAVID analysis." (PMID 40184123, 2025). "SCAMP5 was enriched in low-grade gliomas and isocitrate dehydrogenase mutant gliomas, 1p19q-deficient gliomas." (PMID 40184123, 2025). "In the training group, significant correlations were identified between OS in glioma patients and the following factors: SCAMP5 gene expression, PRS type, age, IDH mutation status, 1p/19q co-deletion status, radiotherapy, temozolomide (TMZ) treatment, and WHO grade." (PMID 40184123, 2025). "In the validation cohort, the expression level of the SCAMP5 gene was also identified as an independent predictor of OS in patients with glioma." (PMID 40184123, 2025). "By leveraging the convenience and precision offered by the CGGA database in collecting and organizing extensive data sets, our objective was to elucidate the correlation between SCAMP5 gene expression and glioma patients." (PMID 40184123, 2025). "We conducted a Cox survival analysis to establish a correlation between SCAMP5 gene expression and the general survival rate of patients with glioma." (PMID 40184123, 2025). "The results of our study indicate that the expression level of the SCAMP5 gene is an independent predictor of OS in patients with glioma." (PMID 40184123, 2025). "The expression of the SCAMP5 gene is correlated with the OS of patients, and the objective was to construct a model for predicting survival in patients with gliomas." (PMID 40184123, 2025). "There is a clear correlation between the expression of the SCAMP5 gene and the overall survival of glioma patients." (PMID 40184123, 2025). "We analyzed the expression of SCAMP5 in different gliomas using the CAAG and developed a prognostic prediction model to predict patients’ survival at 1, 2, 3, 5, and 10 years." (PMID 40184123, 2025). "To further assess the predictive capacity of SCAMP5 gene expression, we constructed a prediction model to estimate OS in glioma patients." (PMID 40184123, 2025). "The objective was to ascertain whether specific factors, including age, SCAMP5 gene expression, radiotherapy, and TMZ chemotherapy, were associated with the survival prognosis of patients with glioma." (PMID 40184123, 2025). "In order to ascertain whether the SCAMP5 gene can be used to predict the prognosis of patients with glioma, we performed K–M and Cox proportional hazard model analyses of the training and validation groups." (PMID 40184123, 2025). "However, the relationship between the SCAMP5 gene and glioma patients remains to be further explored." (PMID 40184123, 2025). "The evidence suggests that the SCAMP5 gene plays a significant function in glioma patients." (PMID 40184123, 2025). "However, how SCAMP5 is expressed and its prognostic value in gliomas is unclear." (PMID 40184123, 2025).
gliomas of the brain (1 paper, 2025). "In GMB multiforme and low-grade gliomas of the brain, SCAMP5 is highly expressed in normal subjects and lowly expressed in tumor patients." (PMID 40184123, 2025).
Hyperglycemia (1 paper, 2025). An increased concentration of glucose in the blood. "Hyperglycemia is likely to activate ChREBP, thereby inhibiting SCAMP5 expression and subsequently causing β‐cell dysfunction." (PMID 40953307, 2025). "In this study, we demonstrate that SCAMP5 expression is reduced in β‐cells under diabetogenic situations, which is involved in hyperglycemia‐activated ChREBP‐mediated reduction of H3K4me3 at the Scamp5 promoter." (PMID 40953307, 2025). "Hyperglycemia is likely to induce β‐cell dysfunction by regulating the ChREBP/SCAMP5 pathway." (PMID 40953307, 2025). "Furthermore, hyperglycemia‐activated carbohydrate‐responsive element‐binding protein (ChREBP) epigenetically represses SCAMP5 expression by reducing trimethylation of histone H3 at lysine 4 (H3K4me3) within the Scamp5 promoter." (PMID 40953307, 2025). "We hypothesized that ChREBP mediates the hyperglycemia‐reduced SCAMP5 expression." (PMID 40953307, 2025).
paraganglioma (1 paper, 2025). A benign or malignant neoplasm arising from paraganglia located along the sympathetic or parasympathetic nerves. "In pheochromocytoma and paraganglioma, SCAMP5 is highly expressed in tumor patients and lowly expressed in the normal population." (PMID 40184123, 2025).
tumor (6 papers, 2012 to 2025). "The NF1::SCAMP5 fusion may disrupt the NF1 tumor–suppressor function while activating SCAMP5-mediated oncogenic pathways, driving myeloid proliferation." (PMID 40761243, 2025). "This highlights the tumor suppressive role of SCAMP5 in PAAD cells." (PMID 33493138, 2021). "Hsa-miR-16, mentioned previously to be anti-correlated in tumours with several potential mRNA targets including E2F3, C8ORF30A, and SCAMP5, is significantly positively correlated with CDC25C." (PMID 22452920, 2012).
cancer (4 papers, 2021 to 2025). A tumor composed of atypical neoplastic, often pleomorphic cells that invade other tissues. "The KEGG analysis shows that SCAMP5 is correlated with the chemokine signaling pathway and cell adhesion molecules (CAMs), so the gene plays an oncogene role in cancer, and it may be used as a diagnostic identifier in cancer." (PMID 40761243, 2025). "Moreover, univariate analysis indicated that age, metastasis, SCAMP1 expression and SCAMP5 expression were significantly associated with the risk of cancer-related death." (PMID 33493138, 2021). "Upon the assessment of an array of cancer cell lines, SCAMPs 1-4 were highly expressed, but SCAMP5 was expressed to lower levels in PAAD cells." (PMID 33493138, 2021). "The GEPIA database shows significant variability in SCAMP5 expression in a few malignant tumors." (PMID 40184123, 2025). "SCAMP5 gene is differentially expressed in different malignant tumors." (PMID 40184123, 2025).
neurodevelopmental disorder (2 papers, 2022 to 2023). A behavioral and cognitive disorder with onset during the developmental period that involves impaired or aberrant development of intellectual, motor, or social functions. "De novo SCAMP5 mutation causes a neurodevelopmental disorder with autistic features." (PMID 38057311, 2023).
neurological disorders (2 papers, 2023 to 2025). "The secretory carrier membrane protein 5 (SCAMP5) plays a distinct role in the cytosolic function of mammalian cells and is associated with different neurological disorders." (PMID 40184123, 2025). "Impaired expression or function of SCAMP5 partly contributes to the abnormal synaptic function and hindered clearance of neurotoxic proteins, leading to potential neurological disorders." (PMID 40184123, 2025). "However, this regulation is essentially preserved with disease-causing SCAMP5 mutations suggesting that T-type channels are likely to not contribute to SCAMP5-mediated neurological disorders." (PMID 37389974, 2023).
movement disorder (1 paper, 2020). Neurological conditions resulting in abnormal voluntary or involuntary movement, which may impact the speed, fluency, quality and ease of movement. "Acquired movement disorder features also have been described in some patients with SCAMP5 heterozygous variant (at about the age of 8 and 10)." (PMID 33390987, 2020).
neurodegenerative disease (1 paper, 2020). A disorder of the central nervous system characterized by gradual and progressive loss of neural tissue and neurologic function. "Similarly, exosome expression of secretory carrier membraneprotein 5 (SCAMP5) is reported to colocalize with and mediate clearance of α-synuclein toattenuate α-synuclein aggregation in neurodegenerative diseases and rescue neuronalfunction impairment and cell death." (PMID 32257533, 2020).
SCAMP5 also shares sentences with these, for which no sentence is quoted: autism spectrum disorder (2 papers); Neurodevelopmental delay (2); pancreatic cancer (2); acute myeloid leukemia (1); brain disorder (1); breast carcinoma (1); cardiovascular diseases (1); colon cancer (1); developmental delay (1); esophageal cancer (1); Glucose intolerance (1); hyperlipidemia (1); Intellectual disability (1); leukemia (1); lung carcinoma (1); melanoma (1); myeloproliferative neoplasm (1); Obesity (1); periodontitis (1); pheochromocytoma (1).